MYC (MYC proto-oncogene, bHLH transcription factor)
Diseases named in the same sentence as MYC in open-access papers (continued):
Sharing a sentence is not in itself a finding about the gene and the disease.
lung carcinoma (continued). "Further evidence for our hypothesis was determined with the indication of the following cancer stem cell markers: GABRP, CTNNB1, and MYC, which are seen in breast, colon, and lung cancer stem cells." (PMID 37370820, 2023). "Mechanistically speaking, LCAT3 facilitated the recruitment of Far Upstream Element Binding Protein 1 to the MYC far-upstream element sequence, thereby triggering MYC gene transcription, which promoted the proliferation, survival, invasion and metastasis of lung cancer cells." (PMID 37915034, 2023). "In addition, a tumor suppressor negatively regulating MYC function in lung cancer, MXI1, was also identified in the selection." (PMID 37251921, 2023). "Lastly, given the similar involvement of MYC in the response to combined Sotorasib and Midostaurin and, more importantly, that MYC amplification has been reported in lung cancer tumors acquiring resistance to Sotorasib50, we tested MYC function in the context of KRASG12Ci treatment." (PMID 37816716, 2023). "As a transcription factor, MYC can enhance the growth and survival of lung cancer and other tumors." (PMID 36982777, 2023). "MYC was recognized as a functional driver of KRAS-mutant LUAD because MYC knockout could eradicate KRAS-driven lung cancer in mice." (PMID 37142594, 2023). "The established primary KPU lung cancer cells expressed higher levels of MYC than KP primary cells." (PMID 38093367, 2023). "Interestingly, Gcn5 has also been shown to be overexpressed in numerous types of cancer cells (colon cancer, Burkitt lymphoma, and lung cancer), in which it functions as a transcription co-activator of the MYC oncogene to promote cell growth." (PMID 37874684, 2023). "The chloroform fraction also inhibited the growth of the A549 spheroid by suppressing the spheroid size, inducing apoptosis, reducing the proportion of CD44 lung cancer stem cells, causing arrest at the S phase of the cell cycle, and suppressing the expression of the SOX2 and MYC genes." (PMID 37513848, 2023). "Interestingly, we found that ARHGs with active copy number increase (e.g. MYC, EIF4EBP1, EGFR) and ARHGs with active copy number loss (e.g. ATG16L1, MTOR, ULK1) also showed high expression in lung cancer tissues." (PMID 35333893, 2022). "This phenomenon indicated that MYC expression drives aberrant lipid metabolism in lung cancer." (PMID 35582412, 2022). "For example, LCAT3 plays an oncogenic role in lung cancer by binding to FUBP1 to activate MYC." (PMID 36482116, 2022). "Furthermore, BRD4 inhibition was shown to reduce the interaction between BRD4 and CDK9 at the MYC locus and prevented the increase in MYC expression caused by i-CDK9 in HeLa, lung cancer, and melanoma cells." (PMID 34207158, 2021). "In the lung cancer cell line A549, MYC-SE activated the occurrence of lung cancer cells." (PMID 33712565, 2021). "In addition to the RNA families let-7, miR-34, and miR-145 mentioned in other sections, the expression of the MYC gene in lung cancer cells is also controlled by miR-199a-5p, miR-449c-5p, and miR-451a." (PMID 34440124, 2021). "Furthermore, USP37 deubiquitinates c-MYC in lung cancer H1299 cells and drives proliferation and the Warburg effect." (PMID 34758854, 2021). "Finally, we analyzed the effect of LCAT3 and FUBP1 on several cell cycle regulatory genes, known to be MYC targets in lung cancer cells." (PMID 34274028, 2021). "Thus, the suppression of MYC expression in lung cancer, melanoma, ovarian cancer, and bladder cancer cells increases the sensitivity of the tumor to cisplatin." (PMID 34440124, 2021).
lung carcinoma (continued). "Indeed, the ChIP assay showed that FUBP1 bound to the c-MYC promoter in lung cancer cells, which is significantly reduced upon LCAT3 knockdown." (PMID 34274028, 2021). "Similarly to what observed in mice, caspase-4 was correlated to the stage of lung cancer in humans in that it induced cell proliferation in a K-Ras, c-MyC and IL-1α dependent manner." (PMID 33187551, 2020). "Similarly, MIR7-3HG upregulation in our analysis contrasts a report showing that MIR7-3HG downregulates the tumor suppressor AMBRA1 and prevents MYC dephosphorylation in lung cancer." (PMID 32260415, 2020). "The positive loop between FACT and c‐MYC can be considered as a therapeutic target in preventing recurrence of lung cancer, since, despite the significant progress in primary treatment of lung cancer, recurrence still occurs after the molecular targeted treatment and immunotherapy." (PMID 31960591, 2020). "Moreover, recent studies addressed the genomic alterations associated with distant metastases, e.g., ESR1 mutations and MYC, YAP1 amplifications enriched in metastatic breast cancer and lung cancer genomes, respectively." (PMID 33287735, 2020). "Additionally, the MYC copy number status was analyzed considering clinicopathological parameters of the lung cancer patients." (PMID 33014186, 2020). "MYC is a classical oncogene, and its amplification is a common event in lung cancer." (PMID 33014186, 2020). "MYC amplification is a common event in lung cancer patients, and it is indicated that the determination of the MYC status might be useful in clinical diagnostics." (PMID 33014186, 2020). "In addition, the expression of PTEN, MYC, EGFR, and Vimentin, potential indicators associated with lung cancer patients survival period, was also detected in A549 lung cancer cells." (PMID 31508368, 2019). "To explore the mechanism by which MYC overexpression in cancer cells correlates with proscillaridin A sensitivity, we compared its effects between MYC driven leukemic cells (MOLT-4 and NALM-6) and low expressing MYC cancers driven by KRAS mutations (SW48 colon and A549 lung cancer cells)." (PMID 31196146, 2019). "Further, the MYC expression is positively associated with AXL, EIF4E, and EMT signatures and both mRNA and protein levels of the EIF4E are of prognostic significance in KRAS-mutant lung cancer, lung adenocarcinoma, and lung cancer." (PMID 31431614, 2019). "Next, we evaluated whether the CTNNBIP1 expression was related to changes in the expression of various β-catenin-targeted genes, such as MMP7, cyclin D1, and c-MYC, among these lung cancer patients." (PMID 31766223, 2019). "Furthermore, aberrant expression of BCL2L1 significantly altered the expression of lung cancer biomarkers such as MYC, EGFR, and Vimentin." (PMID 31508368, 2019). "Interestingly, MYC was among the 28 ORFs found positively enriched in metastases isolated from our primary screen, thereby further supporting its role in lung cancer metastasis." (PMID 30013058, 2018). "Additionally, HIF-1α expression has been significantly correlated with the expression of MYC and survivin in lung cancer." (PMID 29482638, 2018). "A recent study demonstrated that circulating levels of IgG antibodies against linear peptide antigens derived from baculoviral IAP repeat‐containing protein 5 isoform 2 (BIRC5) and myc proto‐oncogene protein (MYC) were significantly increased in nonsmall cell lung cancer (NSCLC)." (PMID 29744296, 2018). "A previous report demonstrates MYC-regulated BC200 expression in the context of lung cancer." (PMID 28651607, 2017). "To this end, we firstly examined capabilities of SFN and miR-214 in modulation of c-MYC accumulation in response to cisplatin, which is a commonly prescribed chemotherapeutic drug for patients with lung cancer and is capable of inducing CSC phenotypes in NSCLCs." (PMID 28076844, 2017).
lung carcinoma (continued). "To better understand the role of GSK-3α and examine the critical genes affected by GSK-3α in lung cancer, we initially screened a subset of NF-κB target genes such as MYC, WT1, BIRC2, IL-9, HMOX1, and TERT, which were regulated by a pan-GSK-3 inhibitor AR-014418 in pancreatic cancer." (PMID 27049759, 2016). "Their co-regulation with MYC further confirmed their correlation with lung cancer." (PMID 26402252, 2015). "Its ten hub genes were extracted and confirmed in the literature; seven of them (UBC, SRC, SP1, MYC, STAT3, RB1, and MAPK1) were verified to be associated with lung cancer, while the remaining three genes, JUN, NR3C1, and GRB2, were potentially new candidate lung adenocarcinoma-related genes." (PMID 26402252, 2015). "In a murine K-RAS-driven lung cancer model designed to reversibly inhibit c-MYC, c-MYC inhibition not only induced regression of incipient and established lung tumors, it also exerted profound effects on normal regenerating tissues, as might be anticipated." (PMID 24130880, 2013). "MYC amplification has been shown to be correlated with poor prognosis of patients with lung cancer." (PMID 22848662, 2012). "Gene set enrichment analysis (GSEA) results suggest that MRPL13 may participate in the development and progression of lung cancer by modulating key signaling pathways such as MYC targets, PI3K/AKT/mTOR signaling, oxidative phosphorylation, and the G2/M checkpoint." (PMID 40371222, 2025). "Given that USP13 regulates the stability of MYC in glioblastoma and hepatocellular carcinoma, contributing to self-renewal or tumorigenic potential, we hypothesized that USP13 would be directly associated with MYC protein abundance in lung cancer." (PMID 38093367, 2023). "Notably, MYC is one of the most frequently amplified genes in lung cancer." (PMID 37858127, 2023). "Thus, MYC was amplified in 58 of 114 tumor tissues of lung cancer patients." (PMID 37858127, 2023). "In addition, in lung cancer cell lines expressing high levels of endogenous MYC and proline synthetic enzymes, a knockdown of proline enzymes or MYC could significantly inhibit tumor growth." (PMID 36090329, 2022). "Next to MYC, NF-κB signaling is broadly described to be involved in multiple steps of lung carcinogenesis, to mediate therapy resistance, and to be active in lymph node metastasis, providing an important linkage between the pathogenesis of pulmonary inflammation and lung cancer." (PMID 33925297, 2021). "Besides, Liu’s research demonstrated that circRNA_103809 could upregulate ZNF121-dependent MYC expression via sponging miR-4302, and finally promote cell proliferation and metastasis in lung cancer." (PMID 32499818, 2020). "Thus, MYC alteration might be a promising biomarker candidate for the detection of lung cancer in tissues." (PMID 33014186, 2020). "Moreover, c-MYC has been recognized as a carcinogen of lung cancer in molecular biology." (PMID 32565880, 2020). "Thus, c‐MYC is required for CPA4 to promote lung cancer cell growth." (PMID 31397502, 2019). "Knockdown of c‐MYC in CPA4‐overexpressing cells blocked the increase of Bcl‐2 and restored the expression of P27, indicating that c‐MYC may be the cause of CPA4 promoting lung cancer growth." (PMID 31397502, 2019). "Furthermore, it was reported that the SNP rs6983267 was correlated with the increased CRC risk by enhancing the response to Wnt signaling pathway and combination with promoter of MYC, which was aberrantly expressed in many kinds of cancers, including lung cancer." (PMID 27249003, 2016). "In addition to the similar CNV profile (e.g., common gains in chromosomes 1, 8, 17, and 20) and gene expression profile (e.g., overexpression of AKT3, MYC) between the breast tumor samples and the ovary/lung cancer cell lines, there are some other commonalities between them." (PMID 26273658, 2015). "As point mutations in MYC do not occur in lung cancer, the gain of MYC could be important for lung cancer classification in never smokers." (PMID 21151896, 2010).
lung carcinoma (continued). "Moreover, our observation that the combined inactivation of both MYC and K-rasG12D induced lung tumor regression more effectively suggests that the K-Ras pathway may be an important target for the treatment of lung cancer." (PMID 18461184, 2008). "Larger prospective studies with standardized scoring systems are warranted to validate these findings and to clarify the clinical utility of c-MYC and EZH2 as potential prognostic and therapeutic biomarkers in lung cancer." (PMID 41928013, 2026). "MYC downregulates H3K27 acetylation and JAK2 expression, impairing the IFN-γ signaling pathway and rendering lung cancer cells resistant to PD1/PD-L1 therapy." (PMID 40166469, 2025). "Of note, AREG, EREG, FOSL1, MYC, and PLAU are involved in the EGFR signaling pathway, which is a key pathway in lung cancer development." (PMID 39858622, 2025). "In most lung cancer cell lines, low expression levels of AMBRA1 and high expression levels of phosphorylated MYC have been reported." (PMID 38393538, 2025). "For instance, USP13 deubiquitinated c-MYC in glioblastoma and lung squamous cell carcinoma to promote disease progression; USP13 oncogenically stabilized MCL-1 in ovarian and lung cancer and de-sensitized tumor cells to BH3 mimetic inhibitors." (PMID 41315297, 2025). "Subsequent fractionation of nuclear and cytoplasmic proteins from lung cancer cells demonstrated that upregulation of RPL35A significantly enhanced the nuclear accumulation of MYC, suggesting that RPL35A facilitate MYC’s nuclear translocation." (PMID 41241099, 2025). "Our study found that in DLBCL, miR-7-5p prevented MYC dephosphorylation through AMBRA1 downregulation, which is consistent with the lung cancer research." (PMID 38393538, 2025). "Additional genes with significant amplification of expression exploit copy number changes, e.g., of Myc transcription factor in pancreatic cancer, and diffuse large B-cell and high-grade lymphoma, and MYC and TERT copy number variations in lung cancer." (PMID 40727661, 2025). "In lung cancer cell lines, BET inhibitors have been demonstrated to suppress cell proliferation and trigger apoptosis by downregulating MYC." (PMID 40191732, 2025). "In summary, this study reveals that RPL35A is highly expressed in lung cancer and promotes SKP2 transcription by facilitating MYC nuclear translocation and enhancing its binding to the SKP2 promoter." (PMID 41241099, 2025). "Further, intracellular levels of SirT1 and AMPK, which are essential factors in supporting MYC expression, can influence MDR characteristics during lung cancer treatment." (PMID 37450923, 2024). "The results from qRT-PCR and Western Blotting showed that, like SNAP25, the expression levels of c-MYC, MEK, and ERK were significantly elevated in HGNEC cells compared to normal lung cells and less malignant lung cancer cells." (PMID 39430761, 2024). "Our results showed that chia extracts; alcohol and ether significantly reduced expression levels of the studied genes c-MYC (by about 96 and 80%) and MMP9 (by about 69 and 60%) compared to the lung cancer group (p ≤ 0.05)." (PMID 39338293, 2024). "In lung cancer, the lncRNA MYMLR was shown to play a role in tumor progression by establishing an enhancer–promoter loop and activating MYC transcription." (PMID 39020380, 2024). "NNK administration stimulated inducible lung cancer biomarkers, including (i) ICAM-1 level, c-MYC, and MMP9 genes, (ii) inflammation, (iii) angiogenesis, and (iv) proliferation." (PMID 39338293, 2024). "To evaluate the anti-lung cancer effect, we estimated three anti-lung cancer biomarkers: Intercellular Adhesion Molecule-1(ICAM-1), MYC proto-oncogene, bHLH transcription factor(c-MYC), and Matrix metalloproteinase-9 (MMP9) genes." (PMID 39338293, 2024).
lung carcinoma (continued). "Cooperation between c-MYC and NOTCH during tumorigenesis has been documented in lung cancer, T-cell acute lymphocytic leukemia, and mantle cell lymphoma and chronic lymphocytic leukemia." (PMID 37175848, 2023). "Small molecules targeting HIF1A-As2 and MYC significantly inhibit tumor growth, suggesting lncRNA HIF1A-As2 presents an important biological and clinical impact in lung cancer, particularly in KRAS-driven NSCLC." (PMID 37041291, 2023). "For example, in pancreatic and lung cancer, it has been reported that oncogenic KRAS mutants stimulate the transcription of NRF2 via JUN and MYC." (PMID 37373496, 2023). "For example, the combined actions of endogenously expressed mutant KRAS and modestly deregulated MYC expression led to NK cell‐mediated immune escape through inhibition of IFN‐I pathways in pancreatic ductal adenocarcinoma and lung cancer." (PMID 35253368, 2022). "Particularly, this family suppresses the proliferation of tumors, like breast and lung cancer, by regulating the expression of critical oncogenes including RAS, MYC, and HMGA2." (PMID 36062186, 2022). "Analysis of the enriched genes derived from the pathway analysis identified seven genes present in both asthma and lung cancer: BCL3, POSTN, PPARD, STAT1, MYC, CD44, and FOSB." (PMID 35406434, 2022). "Analysis of the enriched genes derived from the pathway analysis identified seven genes expressed in both the asthma and lung cancer sets: BCL3, POSTN, PPARD, STAT1, MYC, CD44, and FOSB." (PMID 35406434, 2022). "We performed a correlation analysis between NCAPG2 and 13 lung cancer stemness markers using the TCGA database and found that NCAPG2 was highly correlated with ABCC1, MYC, and EPCAM." (PMID 36139554, 2022). "The ChIP-Seq data of MYC and MAX at the regulatory regions of LINC00958 in lung cancer cells, including H2171 and SW1271 cells, were retrieved from the GEO database (GSM894103, GSM3073948, and GSM3073949) and plotted." (PMID 35223488, 2022). "Conversely, inhibition of GPR87 in lung cancer suppresses tumor proliferation by reducing the expression of KRAS and c-MYC." (PMID 35008182, 2021). "KRT6A regulates the expression of G6PD through c-MYC/MYCN to promote the proliferation and invasion of lung cancer cells." (PMID 34235156, 2021). "Mechanistically, LCAT3 recruited Far Upstream Element Binding Protein 1 (FUBP1) to the MYC far-upstream element (FUSE) sequence, thereby activating MYC transcription to promote proliferation, survival, invasion and metastasis of lung cancer cells." (PMID 34274028, 2021). "Overexpressed LCAT3 then recruit FUBP1 to c-MYC promoter to transactivate c-MYC expression, leading to enhanced proliferation, survival, migration/invasion and metastasis of lung cancer cells." (PMID 34274028, 2021). "Here, we present evidence that CPF is able to impede the proliferative switch of quiescent lung cancer cells by transcriptional suppression of FACT and c‐MYC genes." (PMID 31960591, 2020). "This family in particular inhibits the progression and invasiveness of numerous tumors, including lung cancer, by regulating the expression of key oncogenes such as RAS, MYC, and HMGA2." (PMID 31031083, 2019). "In lung cancer, circular RNA hsa_circRNA_103809 acts as an oncogene through miR-4302/ZNF121/MYC axis." (PMID 31703640, 2019). "Evidences of this dual role include the down-regulation of MYC and HER2 by FOXP3+ Tregs, and the up-regulation of FOXP3 protein in both Tregs and tumor cells in patients with lung cancer and hepatocellular carcinoma." (PMID 30782783, 2019). "In the multivariable analysis, only lung cancer as well as the presence of ARID1A, KRAS, ALK, and MYC alterations and liver metastasis remained significant predictors of a poorer survival (all P < 0.50)." (PMID 29866143, 2018).